HMGB1 (high mobility group box 1)
Diseases named in the same sentence as HMGB1 in open-access papers (continued):
Sharing a sentence is not in itself a finding about the gene and the disease.
tumor (continued). "Elevated ROS levels not only impair tumor cell viability but also promote the release of key DAMPs such as ATP, HMGB1, and CRT." (PMID 40299564, 2025). "On the other hand, HMGB1 plays an important role in tumor suppression, regulating the effects of tumor radiotherapy and immunotherapy, and even in cancer prediction." (PMID 41296391, 2025). "Gemcitabine induces tumor antigen release (such as HMGB1) and reduces myeloid-derived suppressor cells (MDSCs), while CD40 agonists enhance the expression of co-stimulatory molecules (CD80/86), drive CD8+ T cell infiltration and inhibit Treg function." (PMID 41293424, 2025). "NET-derived HMGB1 further promotes tumor growth by activating RAGE and TLR9, leading to MAP kinase and NF-kB signaling." (PMID 41335221, 2025). "In the current study, we emphasized the importance of HMGB1, which was markedly overexpressed in tumor tissues when compared with that in normal hepatocytes." (PMID 40331953, 2025). "Impaired or dead tumor cells release damage-associated molecular patterns (DAMPs) including ATP, calreticulin (CRT) and high mobility group box 1 (HMGB1) to activate dendritic cells (DCs) and subsequent T cells for anti-tumor immunity initiation." (PMID 39776799, 2025). "As a cell surface receptor, RAGE is widely expressed on both tumor and immune cells and recognizes multiple secretory substrates, including HMGB1 and S100 proteins, triggering downstream inflammation-related signaling cascades." (PMID 39893499, 2025). "Studies have shown that asbestos fibers stimulate both immune and MM cells to secrete acetylated HMGB1, which subsequently activates receptor-mediated signaling pathways and triggers inflammatory responses that promote tumor progression." (PMID 40559922, 2025). "Ferroptosis induces tumor cell death through lipid peroxidation, accompanied by the release of immune-stimulatory signals (such as ATP and HMGB1), forming a synergistic effect with ICD." (PMID 40535125, 2025). "Conversely, substantial evidence demonstrates that HMGB1 release during pyroptosis can potentiate anti-tumor immunity and treatment response." (PMID 41465435, 2025). "In macrophages, lactate activates GPR65, promotes downstream cAMP/PKA/CREB activation, facilitates HMGB1 secretion and promotes tumor cell proliferation." (PMID 40165895, 2025). "Tumor cells undergoing ferroptosis release DAMPs, such as HMGB1 and ATP, which trigger immune activation through the cGAS–STING pathway." (PMID 40919133, 2025). "The pyroptosis‐related markers NLRP3, HMGB1, and caspase‐1 are known to regulate inflammatory signaling and modulate the tumor microenvironment." (PMID 41479846, 2025). "The group demonstrated that HMGB1 expression correlates with γ-H2AX expression, a key marker of DNA damage in tumor cells after RT, highlighting the interplay between HMGB1 and RT-induced DNA damage in cancer cells." (PMID 41332426, 2025). "α-Smooth muscle actin (α-SMA), the EMT marker, was significantly increased in HMGB1-overexpressed tumor tissues and was reduced by ICM and Stattic treatments." (PMID 40389855, 2025). "These approaches are expected to further contextualize the molecular insights regarding the HMGB1/ZNF460/BECN1 axis within the broader “tumor ecosystem” framework, thereby offering a more comprehensive strategy to address radiotherapy resistance in CRC." (PMID 41164196, 2025). "HMGB1 is reportedly involved with various tumor mechanisms, including tumor growth, metastasis, angiogenesis, and chemoresistance." (PMID 40331953, 2025). "HMGB1 drives tumor metabolic reprogramming by directly intervening in glycolysis, oxidative phosphorylation (OXPHOS), the tricarboxylic acid (TCA) cycle, and mitochondrial energy homeostasis." (PMID 41354099, 2025). "ADCC recruits NK cells and macrophages to tumor cells, releasing DAMPs (HMGB1, ATP, CRT) that activate DCs via TLR4/cGAS–STING pathways, enhancing antigen cross-presentation and CD8+ T-cell priming." (PMID 40989107, 2025).
tumor (continued). "The state of DCs in tumors can be altered by HMGB1 released by tumor cells, affecting their maturation and antigen-presenting capabilities, transitioning them into a tolerant state that promotes tumor development." (PMID 40441235, 2025). "The T cell immunoglobulin mucin receptor 3 (TIM3), expressed on tumor-infiltrating cDCs, competes with tumor-derived DNA for binding to HMGB1." (PMID 41176596, 2025). "The disulfide‐linked form of HMGB1 induces VEGF‐A secretion via TLR4, whereas the fully reduced thiol form mediates endothelial cell migration via RAGE, collectively promoting tumor angiogenesis." (PMID 41354099, 2025). "Subsequently, many intracellular components, including IL-1β, HMGB1, and tumor antigens, were rapidly released." (PMID 40698137, 2025). "Future research should aim to elucidate the context-specific roles of HMGB1 within the tumor microenvironment and to develop safe and effective HMGB1-targeted agents." (PMID 40969278, 2025). "We also examined the impact of HMGB1 on tumor progression, immune responses, and metabolic reprogramming in cancer cells, as well as its role in inflammatory signaling pathways." (PMID 41354099, 2025). "We found that while HMGB1 knockdown slightly slowed tumor growth, it also abrogated the therapeutic efficacy of the recombinant viruses." (PMID 40082916, 2025). "Under conditions such as nutrient deprivation, oxidative injury, hypoxia, and exposure to DNA-damaging therapy, HMGB1-driven autophagy allows tumor cells to endure stress, evade apoptosis, and reconfigure their metabolism." (PMID 41465435, 2025). "In summary, we demonstrated that NE or PPE expressed by the recombinant viruses ADVNE and ADVPPE induces the release of HMGB1 from tumor cells, leading to the M1 polarization of macrophages in the tumor microenvironment." (PMID 40082916, 2025). "For instance, the transcriptional regulator Yes-associated protein (YAP) promotes both the expression and the cytosolic translocation of HMGB1, thereby enhancing autophagy and tumor progression in gliomas." (PMID 41465435, 2025). "In xenograft models, treatment with ethyl pyruvate (EP) and TAK-242 significantly suppressed tumor growth and HMGB1 expression, reinforcing their therapeutic potential." (PMID 40559922, 2025). "This led to the accumulation and release of DAMPs—CRT, HMGB1, and ATP—from tumor cells, events that can help breach the immune-exclusive TME." (PMID 41304839, 2025). "It was found by immunofluorescence experiments that both CPP and CPPM were able to increase the expression of CRT on the cell membrane under PDT, while HMGB1 was significantly attenuated in tumor cells." (PMID 40491506, 2025). "EC cells release high-mobility group box 1 (HMGB1), an evolutionarily conserved DNA-binding nuclear protein, into the tumor microenvironment." (PMID 40136652, 2025). "The enhanced release of HMGB1 from pyroptotic tumor cells subsequently increases the expression of CXCL2 in neighboring tumor cells, which recruit MDSCs into the tumor microenvironment, thereby promoting CRC development." (PMID 40213993, 2025). "TIM-3 interacts with four distinct ligands: galectin-9, phosphatidylserine (PtdSer), high-mobility group protein B1 (HMGB1), and carcinoembryonic antigen-related cell adhesion molecule-1 (CEACAM-1), all of which are implicated in tumor progression." (PMID 40565041, 2025). "Doxorubicin specifically promotes eIF2α phosphorylation, triggering ER stress and autophagy activation to enhance CRT and HMGB1 surface exposure, thereby boosting tumor immunogenicity." (PMID 40900811, 2025). "The so-called “cold” tumor milieu was converted into a “hot” immune-active state, characterized by the overexpression of HMGB1, a marker of immunogenic cell death, and a substantial increase in CD3+ CD8+ cytotoxic T-cell infiltration." (PMID 40949866, 2025). "The functional duality of HMGB1 is consistent with Hanahan’s cancer hallmarks, demonstrating context-dependent oncogenic or tumor-suppressive effects." (PMID 40969278, 2025).
tumor (continued). "HMGB1 has been defined as one of the cancer prognostic markers that mediates tumor progression and resistance." (PMID 41301513, 2025). "The fact that HMGB1 is expressed not only in cancer cells but also in virtually all cell types of the tumor microenvironment adds further complexity and constitutes a challenge for studying HMGB1 in cancer in vivo." (PMID 40804938, 2025). "Adenosine Triphosphate (ATP) and High Mobility Group Box 1 (HMGB1) are DAMPs secreted or released by tumor cells, whereas others, such as calreticulin (CRT) and heat shock protein 90 (HSP90), are exposed de novo or overexpressed by both tumor and immune cells." (PMID 39857785, 2025). "Numerous studies demonstrate that HMGB1, upon release from stressed or dying tumor cells, engages RAGE, TLR4, or TNFR1 to initiate canonical NF-κB activation, resulting in phosphorylation of IKKα/β, degradation of IκBα, and nuclear translocation of p65." (PMID 41465435, 2025). "Secondly, the dualistic nature of HMGB1, functioning both as a tumor promoter and an immune activator, highlights the complexity of its role across various stages of tumor progression and therapeutic intervention." (PMID 40969278, 2025). "In the MC38 model, enhanced perfusion during radiation therapy increased the release and distribution of tumor antigens, as shown by elevated serum HMGB-1 levels." (PMID 40568078, 2025). "In synergy with immunotherapy, dying tumor cells undergoing ferroptosis or cuproptosis release a series of damage-associated molecular patterns (DAMPs), including ATP, calreticulin (CRT), and high-mobility group box 1 (HMGB1)." (PMID 41201667, 2025). "Specifically, we investigated the translocation of CLR from the endoplasmic reticulum to the plasma membrane and the release of high-mobility group box 1 protein (HMGB1) from dying tumor cells." (PMID 40007542, 2025). "Polyphenols such as EGCG promote autophagic degradation of intracellular HMGB1 and reduce extracellular HMGB1 release, thereby lowering HMGB1-mediated inflammasome activation and tumor-promoting inflammation." (PMID 41465435, 2025). "Malignant tumor cells showed limited expression of all genes in tumor cells, except for HMGB1, which had prominent high expression." (PMID 40535567, 2025). "We demonstrated that HMGB1 is a crucial element in tumorigenesis and tumor metastasis, both in vitro and in clinical settings." (PMID 40331953, 2025). "Surface-exposed CRT functions as a phagocytic “eat-me” signal that facilitates dendritic cell (DC) uptake of dying tumor cells, while HMGB1 and ATP serve as potent stimulators of DC maturation and enhanced antigen presentation capacity, respectively." (PMID 40835706, 2025). "Tumor growth in time course and tumor volume at 4 weeks after inoculation showed that MT inhibition suppressed tumor growth, especially HMGB1 antibody treatment." (PMID 39940960, 2025). "Because of the ubiquitous expression of HMGB1 in virtually all cell types of the tumor stroma, IHC is the optimal method for assessing the HMGB1 status of a tumor." (PMID 40804938, 2025). "As these events are interconnected, it is challenging to pinpoint which event or combination of events is responsible for the altered HMGB1 concentration in tumor-bearing mice and treated mice." (PMID 40007542, 2025). "NET formation by vital NETosis boosts HMGB1 production in tumor cells, activating TLR9-dependent pathways and the TLR4/9-COX2 pathway, which improve tumor cell survival and invasion." (PMID 40655142, 2025). "A positive Pearson correlation was found between the HMGB1 level and the primary tumor size (p < 0.0001) or the flank tumor size (p = 0.0005)." (PMID 40400098, 2025). "Mechanistically, heat-shock conditioning is known to enrich tumor cell lysates in DAMPs (e.g., HMGB1, HSP70/HSP90), which cooperate with tumor-associated antigens to license DC." (PMID 41439959, 2025). "PD-L1 and TIM3 ligands (LGALS9, PTDSS1, CEACAM1, and HMGB1) were identified on macrophages, DCs, and tumor cells." (PMID 40027748, 2025).
tumor (continued). "Previous studies suggest that HMGB1 can inhibit aerobic respiration and alter mitochondrial metabolism, potentially leading to tumor cell death under low-oxygen conditions." (PMID 40507337, 2025). "Nuclear HMGB1 translocates to the extracellular space under hypoxic conditions depending on tumor growth and the inflammatory tumor microenvironment." (PMID 40244228, 2025). "Based on our results, the high HMGB1 levels in our animal model are likely supportive of a pro‐tumor response instead of an anti‐tumor response." (PMID 40400098, 2025). "Our research demonstrated that IFNG facilitated tumor angiogenesis via HMGB1 pathways, mitigated by HMGB1 inhibition." (PMID 39945555, 2025). "RT-induced tumor cell DNA breaks leading to the genomic instability that triggers tumor cell apoptosis, the release of high mobility group box 1 protein (HMGB1) and ATP, and the translocation of calreticulin on the tumor cell surface (eat-me signal)." (PMID 40141437, 2025). "In this study, we evaluated HMGB1 expression in CRC through an analysis of a public tumor database and two paired tissue microarrays (TMAs)." (PMID 40975711, 2025). "In the tumor microenvironment, extracellular HMGB1 increases various inflammatory cytokines and chemokines and promotes tumor growth, angiogenesis, and metastasis through TLR4 and RAGE." (PMID 40389855, 2025). "Recent studies have underscored the pivotal role of mitochondria in promoting tumor chemoresistance, particularly through mechanisms involving dynamin-related protein 1 and high-mobility group box 1 protein." (PMID 40109861, 2025). "On one hand, it can induce immunogenic cell death (ICD) in tumor cells, releasing DAMPs such as ATP, HMGB1, and calreticulin, which promote dendritic cell (DC) maturation and T cell activation, thereby enhancing anti-tumor immune responses." (PMID 41407677, 2025). "In one study, HMGB1 was found to interact with tumor-infiltrating DCs, suppressing nucleic-acid-mediated antitumor activity in mice with established tumors." (PMID 38994937, 2024). "These domains, together with the various binding sites, allow HMGB1 to perform vital roles in cellular processes, including immune regulation and tumor development." (PMID 38725632, 2024). "Future research can further explore the molecular mechanisms of the HMGB1/RAGE axis in tumor cell apoptosis, search for more anti-tumor drugs, and investigate their relationship with the HMGB1/RAGE axis." (PMID 38529373, 2024). "DAMPs, which mainly consist of High Mobility Motif Box 1 (HMGB1), mitochondrial DNA and ATP‐binding immune cells or tumour cell surface receptors, have a dual function in tumour immunity." (PMID 38652105, 2024). "On the one hand, HMGB1 can be rapidly released from dead and necrotic tumor cells as an alarmin upon treatment with chemotherapy or radiotherapy." (PMID 38347600, 2024). "One of the most interesting ligands based on the carcinogenic effect during development tumor was HMGB1." (PMID 39669558, 2024). "The HMGB1/RAGE axis also profoundly impacts the tumor microenvironment by activating the γδ T cell population." (PMID 38529373, 2024). "For instance, 1-stearoyl-2-15-hydroxyeicosatetraenoic acid phosphatidylethanolamine (SAPE-OOH) and HMGB1 are released during tumor ferroptosis and bind to TLR2 and RAGE receptors." (PMID 39575419, 2024). "HMGB1 participates in several biological activities including inflammation, cell differentiation, and tumor cell migration." (PMID 38331967, 2024). "Oncolytic peptides can act directly on tumor cells and release DAMPs such as Calrein, ATP, HMGB1, mtDNA, and formyl peptides after tumor killing." (PMID 39076973, 2024). "Functional experiments demonstrated that HMGB1 knockdown significantly suppressed tumor proliferation and malignancy, reinforcing the therapeutic potential of targeting necroptosis." (PMID 39717781, 2024).
tumor (continued). "Blocking TIM3 has shown to promote the activation of conventional DCs (cDC) in tumors, increase the responsiveness to cisplatin treatment (known to trigger the release of HMGB1) and the efficacy of DNA–based tumor vaccines in mouse models." (PMID 39759854, 2024). "The immune system recognizes cytokines released by dead tumor cells (high mobility group protein B1 (HMGB1), heat shock proteins (HSPs), S100, oxidized DNA, ATP, etc.) and further presents them to CTL, releasing TNF, including TNF- α And IFN- γ." (PMID 38339426, 2024). "Experimental evidence has shown that inhibiting the HMGB1/RAGE axis can suppress tumor angiogenesis." (PMID 38529373, 2024). "Extracellular HMGB1 can induce M1-like polarization of TAMs in the tumor microenvironment of glioblastoma, activating the ERK1/2/NF-κB/NLRP3 inflammatory pathway and promoting the release of various cytokines (e.g., IFN-γ, IL-6, TNF-α, and IL-8)." (PMID 37897664, 2024). "In vivo experiments using HMGB1 antibodies successfully targeted and inhibited tumor angiogenesis in the chorioallantoic membrane (CAM) of chick embryos." (PMID 38529373, 2024). "Glycyrrhizic acid is a specific inhibitor of high mobility group box 1 (HMGB1), which regulates DNA structure but can be released into the extracellular space, playing a tumor-promoting role in HCC by stimulating tumorigenesis, proliferation, and metastasis." (PMID 39354529, 2024). "Hypoxic tumor cells produce cytokines such as oncostatin, HMGB-1, TGF-β, or IL-6 to promote an alternative macrophage (M2) polarization and tumor progression." (PMID 39256888, 2024). "HMGB1 is released into the extracellular space and binds to Toll-like receptors (TLRs), ensuring the optimal processing and presentation of tumor antigens by DCs." (PMID 39916954, 2024). "In order to study the in vivo mechanism by which BMAL1 regulates ferroptosis through HMGB1, we utilized subcutaneous tumor implantation to establish AML tumor models." (PMID 38703241, 2024). "It is worth noting that HMGB1 has the potential to enhance the effectiveness of certain drugs, as evidenced by its ability to augment the cytotoxic impact of cisplatin on tumor cells." (PMID 39008169, 2024). "In cancer immunotherapy models, knocking out HMGB1 in tumor cells or neutralizing HMGB1 with specific antibodies can notably reduce the tumor-suppressing capacity." (PMID 39916954, 2024). "The high mobility group protein (HMGB1), a conserved nuclear protein, plays a pivotal role in carcinogenesis by stimulating tumor cell growth and migration." (PMID 38577597, 2024). "The binding of HMGB1 to RAGE can activate multiple signaling pathways, including NF-κB, MAPK, MEK, ERK1/2, PI3K, Akt, and TGF-β, which are associated with tumor progression." (PMID 38529373, 2024). "Over-expression of HMGB1 was observed in 55.7% cases and significantly correlated with tumour invasion, lymph node involvement, distant metastases and Duke’s stage, and staining in adjacent normal mucosa was weaker." (PMID 38353760, 2024). "Docetaxel can potentially enhance anti-tumor efficacy by increasing the secretion of HMGB1 and CXCL11, consequently promoting the recruitment of CD8+ T cells into the tumor microenvironment." (PMID 38850524, 2024). "In vitro experiments demonstrated that exogenous HMGB1 increased the expression of RAGE and TLR4 in ECs, further confirming that RAGE is the primary receptor for HMGB1 in tumor ECs." (PMID 38529373, 2024). "Second, treatment with decitabine, which induces demethylation of the PARK2 promoter and reexpression of endogenous PRKN in tumor cells, also induced HMGB1 release in the CM of multiple tumor types." (PMID 39213189, 2024). "This process involves the exposure of calreticulin (CRT) on the tumor cell surface, as well as the release of high mobility group box 1 (HMGB1) or adenosine triphosphate (ATP), which attract dendritic cells (DCs) for phagocytosis and antigen presentation." (PMID 38724527, 2024).